IDO1 (indoleamine 2,3-dioxygenase 1)
Diseases named in the same sentence as IDO1 in open-access papers (continued):
Sharing a sentence is not in itself a finding about the gene and the disease.
tumor (continued). "The impact of codelivering the STING agonist and IDO1 inhibitor on the immune system was evaluated by analyzing the immune cell phenotypes in the tumor tissues and immune organs." (PMID 41129257, 2025). "Tryptophan, on the other hand, is catabolized by tumor‐ and myeloid‐expressed indoleamine 2,3‐dioxygenase 1 (IDO1), resulting in local tryptophan depletion and accumulation of kynurenine (Kyn), an immunosuppressive metabolite." (PMID 40940612, 2025). "IDO1 expression upregulation is positively related to both tumor cell metastasis and a poor prognosis for tumor patients." (PMID 40686517, 2025). "To begin to address this limitation, we have expanded our observation to different human IDO1-expressing tumor cell lines, and we observed a similar IDO1 stabilization in response to three different catalytic inhibitors." (PMID 41262240, 2025). "Polish cohort patient characteristics according to IDO-1 IHC-status of tumor cells and immune cells." (PMID 40475772, 2025). "Combined with external γ-ray radiation therapy, it can trigger a cascade of immunogenic cell death (ICD) in tumor cells and deplete tryptophan by inhibiting IDO-1, reversing the immunosuppressive tumor microenvironment." (PMID 39861694, 2025). "This outcome highlighted crucial gaps in biomarker-driven patient selection, as well as the need to understand tumor microenvironment heterogeneity and IDO1 expression levels in order to enhance future trial designs." (PMID 41035912, 2025). "IDO1 is a pivotal immunoregulatory enzyme mostly expressed in immune cells, astrocytes, and some tumor cells, and it significantly contributes to cancer immunoregulation and cellular metabolism." (PMID 40708940, 2025). "Differences in IDO1 expression between common tumor cells and cancer stem cells offer insights for optimizing cancer treatment strategies." (PMID 40103267, 2025). "We observed in both patients that IDO1 positive tumor cells displayed a higher percentage of GLI and STAT1/IRF1 double positive cells than IDO1 negative tumor cells." (PMID 39962447, 2025). "Taken together, our results indicated that IDO1 inhibitors suppressed the tumor growth in C1498 AML-bearing mice." (PMID 40234305, 2025). "Third, the selection of the appropriate IDO1 inhibitor should be tailored to the specific Trp metabolic pathways involved in each tumor type." (PMID 40959206, 2025). "We randomly collected human GBM specimens and adjacent non-tumor tissues and performed IDO1 immunohistochemistry (IHC) staining." (PMID 39863603, 2025). "The PROTAC component is selectively activated in the tumor microenvironment through cathepsin B-mediated cleavage, ensuring precise spatial and temporal control of IDO1 degradation." (PMID 40894232, 2025). "Aberrant IDO1 expression is involved in tumor immune escape, which makes it an anti‐cancer target under investigation." (PMID 40062505, 2025). "Due to IDO1’s moonlighting feature, the non-enzymatic conformation of the protein plays a relevant, cell-specific role that must be considered when developing candidate drugs that have to target IDO1 in the TME populated by both tumor and immune cells." (PMID 41262240, 2025). "Previous studies have found that the abnormal expression of TDO2 and IDO1 is related to tumor invasiveness." (PMID 40103267, 2025). "Third, the released NO not only synergistically induces tumor oxidative stress with ·OH but also collaborates with released 1‐MT to inhibit IDO1 expression." (PMID 39661740, 2025). "Inhibiting IDO1, one of the key enzymes involved in tumor immune escape, reduces the functional suppression of T cells by tumors and improves the effector function of immune cells in the tumor microenvironment." (PMID 40808836, 2025). "Altogether, we examined changes in the proteome during tumor-induced conversion of DC2s to DC3s and demonstrate this is accompanied by an increase in functionally active IDO1 and LGMN." (PMID 40789452, 2025).
tumor (continued). "Linrodostat occupies the heme cofactor binding site to block IDO1 activation, preventing tumor immune evasion." (PMID 41035912, 2025). "The catalytic inhibitors of the immunoregulatory enzyme indoleamine 2,3-dioxygenase 1 (IDO1) are investigational drugs for cancer that have been developed with the rationale of reinvigorating the immune responses against the tumor." (PMID 41262240, 2025). "IDO1 is a monomeric heme-containing cytosolic enzyme that plays a significant role in tumor progression." (PMID 40332338, 2025). "A co-culture of AML cells with healthy human PBMCs was established to simulate the tumour immune microenvironment and was used to test the effects of IDO1 in AML cells on B cell subpopulations including their proportions and functions." (PMID 40234305, 2025). "Given prior evidence that glycolysis inhibition impairs tumor growth and that IDO1 blockade restores anti-tumor immunity, combining these strategies presents a promising but underexplored approach." (PMID 40917745, 2025). "As a result, despite their expected anticancer effects, an unintended side effect of IDO1 catalytic inhibitors protects tumor survival and negates the therapeutic potential of these candidate molecules." (PMID 41262240, 2025). "The enzyme indoleamine 2,3-dioxygenase 1 (IDO1), highly expressed by tumor cells and immunosuppressive myeloid cells like dendritic cells and macrophages, catabolizes the essential amino acid tryptophan into kynurenine." (PMID 41471036, 2025). "In glioma, IDO1 levels positively correlate with the WHO tumor grade, IDHwt status, the mesenchymal subtype, and Treg expansion." (PMID 40895574, 2025). "Indoleamine 2,3-dioxygenase 1 (IDO1) has emerged as a pivotal regulator of tumor immune evasion through its intricate modulation of tryptophan (Trp) catabolism." (PMID 40894232, 2025). "IDO-1 expression was determined to be greater in tumor immune infiltrate, with 406 patients (93.8%) determined as positive." (PMID 40475772, 2025). "IDO1 contributes to tumor progression through immune suppression, tolerogenic APC induction, and MDSC-mediated effects, as detailed in the Mechanisms section." (PMID 41035912, 2025). "DAU impacts the downstream target of HCK/IDO1, which inhibits tumor progression by promoting ferritinophagy." (PMID 41438182, 2025). "Our findings indicate that SAMD9 is co-expressed with these immune inhibitory molecules (PD-L1, IDO1) within immunosuppressive tumor subset, potentially attributed to sustained IFN stimulation." (PMID 41331572, 2025). "IDO-1 is overexpressed in multiple tumor types and can be used for immune escape by increasing Trp catabolism and inhibiting T cell activation." (PMID 40696413, 2025). "In the tumor microenvironment, the overexpression of indoleamine 2,3-dioxygenase 1 (IDO1) reprograms Trp metabolism toward kynurenine synthesis, depleting local Trp pools." (PMID 41040871, 2025). "IDO1 catalyzes Trp to kynurenine, which drives impaired T cell proliferation, promotes regulatory T cell expansion, and tumor progression." (PMID 40789452, 2025). "Tumors can create an immunosuppressive environment by overexpressing IDO1, inhibiting anti-tumor immune responses." (PMID 40715093, 2025). "There was a significant positive correlation between IDO-1 positive tumor cells and immune cells (0.2167, p < 0.001)." (PMID 40475772, 2025). "Overexpression of IDO1 in tumor cells and stromal immune cells results in tryptophan depletion and KYN accumulation, which suppress antitumor T-cell responses and promote regulatory T-cell differentiation." (PMID 40869331, 2025). "The IDO1-kynurenine pathway has been shown to also shape the cellular landscape of the tumor immune microenvironment." (PMID 39962447, 2025). "Concurrently, IDO1 activation enhances Treg induction via the AhR-TGF-β1 axis, which cooperates with M2 tumor-associated macrophages to construct a tolerogenic immune niche." (PMID 41040871, 2025).
tumor (continued). "First, selecting the appropriate IDO1 expression threshold for patient enrollment is crucial, as this threshold can vary significantly across different tumor types." (PMID 40959206, 2025). "Our exploratory study shows that IDO1 tumour expression is mainly correlated with inflammatory (blood) markers and TDO2 expression predominantly with patient characteristics such as age, gender, smoking habit and medication use in newly diagnosed GBM patients." (PMID 40471422, 2025). "IDO1 catalytic inhibitors were developed based on the idea of blocking the IDO1 enzyme, a recognized immunocheckpoint that allows tumor growth in the microenvironment." (PMID 41262240, 2025). "In the tumor microenvironment, however, our understanding of how phosphorylated IDO1 influences immune signaling pathways is limited, and the response of other IDO1‐expressing cells, apart from pDCs, to their microenvironment remains to be studied." (PMID 40103267, 2025). "IDO1 inhibitor monotherapy reduces intratumoral kynurenine levels by over 80% and inhibits tumor growth, while combination with anti-PD-L1 antibodies further enhances efficacy." (PMID 41488637, 2025). "For instance, epacadostat reduces IDO1 enzymatic activity but stabilizes its apolipoprotein form, activating a signaling pathway that promotes tumor growth." (PMID 41332472, 2025). "Targeting IDO1 selectively has demonstrated enhanced anti-tumor effects when combined with EpCAM/CD3-bispecific antibodies in BRCA with high IDO1 expression, underscoring its clinical importance." (PMID 40061889, 2025). "GBM tumors exploit this pathway by overexpressing enzymes such as IDO1 and arginase-1, allowing the tumor cells to rapidly consume tryptophan and arginine." (PMID 40507361, 2025). "The effect of IDO1 inhibitors is minimal when used alone, but when combined with immune checkpoint inhibitors, the anti-tumor effect is significantly enhanced." (PMID 39940736, 2025). "Of these 437 patients, corresponding to 1,165 tumor specimens, we evaluated IDO-1-expression levels by IHC both in tumor cells and in immune infiltrate." (PMID 40475772, 2025). "Of the 122 remaining patients, corresponding to 259 evaluable tumor specimens, we analyzed IDO-1-expression by IHC in tumor cells, resulting in 84 patients (67.7%) IHC-negative (IHC-) and 40 patients (32.3%) IHC-positive (IHC+)." (PMID 40475772, 2025). "Previous studies in several cancers demonstrated that interferons produced by tumor-infiltrating leukocytes regulate immunosuppressive PD-L1, PD-L2, and IDO1 through JAK/STAT signaling." (PMID 40449595, 2025). "Ido1 is a rate-limiting enzyme that catalyzes the conversion of the essential amino acid tryptophan to kynurenines and has been extensively studied in tumor-related research." (PMID 41208887, 2025). "Building on these findings, STING agonist monotherapy was anticipated to inadvertently upregulate IDO1 and potentially, prompt to tumor escape, despite provoking robust tumor-specific immune responses." (PMID 41129257, 2025). "Increased TDO and IDO1 activities lead not only to excessive L-Kyn production but also facilitates invasive tumor growth and tumor cell survival." (PMID 40559444, 2025). "The tryptophan–IDO1–kynurenine axis exemplifies how metabolic intermediates act as immune checkpoints, dampening cytotoxic immune responses and facilitating tumor immune escape." (PMID 41562065, 2025). "Despite promising first results, further confirmatory data are needed to establish its efficacy across diverse tumor types, particularly given tumor heterogeneity and varying IDO1 expression in the tumor microenvironment." (PMID 41035912, 2025). "IDO1 expression depends on IFN-ɣ release creating a trap for tumor-infiltrating effector and cytotoxic T cells." (PMID 40895574, 2025). "The present study indicates that IDO1 acts as an oncogene by suppressing the ferroptotic cell death pathway and promoting tumor progression in patients with GBM." (PMID 39863603, 2025).
tumor (continued). "The 1,2,3-triazole motif exhibits diverse pharmacological activities, including anti-tumor, antiviral, anti-inflammatory, and antibacterial effects, making it a valuable scaffold for the design of IDO1 inhibitors." (PMID 41050410, 2025). "In preclinical models, IDO1 inhibition has been shown to reduce the tumor volume, suggesting a therapeutic strategy to enhance the efficacy of immunotherapies in HPV-associated cancers." (PMID 40282436, 2025). "Non-targeted metabolomics also demonstrated that fucoidan interfered with tryptophan metabolism through Bifidobacterium and Lactobacillus, thereby suppressing IDO1 (indoleamine 2,3-dioxygenase 1) expression in tumor tissues." (PMID 41012316, 2025). "Hereby, IDO1 creates a protumor, immunosuppressive environment that accelerates tumor growth and resistance to immunotherapy." (PMID 40789452, 2025). "Altogether, these data demonstrate that IDO1 catalytic inhibitors promote in the FTC-133 tumor cells an intrinsic side effect that enables the cells to migrate and proliferate faster than the control cells, resulting in a pro-tumorigenic effect." (PMID 41262240, 2025). "Indoleamine 2,3-dioxygenase 1 (IDO1) inhibitors have been developed with the aim of reinvigorating antitumor T-cell responses in the tumor microenvironment by blocking the conversion of the essential amino acid tryptophan into immunoregulatory kynurenines." (PMID 41262240, 2025). "IDO1 inhibitory activities and anti-tumor effects of epacadostat, 1-methyl-L-tryptophan (1-L-MT) and RY103 in CT26 colorectal cancer, KPIC pancreatic carcinoma, GL261 glioma and B16F10 melanoma mouse models have been demonstrated." (PMID 40234305, 2025). "Compelling evidence indicated that higher GBM-infiltrating T-cell levels were consequently related to increased tumor IDO1 expression and a corresponding decrease in overall survival (OS) for patients with GBM." (PMID 39863603, 2025). "IDO-1 expression by IHC status was considered independently in tumor cells and immune cells; it was considered as expressed in tumor cells with H-Score ≥ 1 and as expressed in immune cells with percentage ≥ 1%." (PMID 40475772, 2025). "We indeed verified that treatment with STING agonists such as MSA-2 induced IDO1 overexpression in cells of the tumor as well as those of the immune system." (PMID 41129257, 2025). "1-MT is often used as an IDO1 inhibitor in immune regulation and tumour immune evasion studies because it competitively binds to the active site of IDO1, preventing tryptophan from entering the enzyme’s catalytic center." (PMID 40916319, 2025). "Australian cohort patient characteristics according to IDO-1 IHC-status of tumor cells and immune cells." (PMID 40475772, 2025). "The proportion of tumor cells with IDO1 overexpression, however, is highly variable between different tumors." (PMID 40512849, 2025). "This metabolic-immune crosstalk highlights how Wnt5a-driven IDO1 activity facilitates immune escape and sustains metabolic plasticity, thereby supporting tumor progression." (PMID 40917745, 2025). "Overall, these data suggest an additional “on-target” effect of IDO1 catalytic inhibitors in the different tumor cell lines." (PMID 41262240, 2025). "Previous studies have determined that in gastric adenocarcinoma patients who harbor high levels of IDO1 and TDO2, these enzymes can promote tumor progression and are associated with a worse prognosis." (PMID 40092297, 2025). "None of the analyzed variables (age, sex, histology, stage, EGFR, KRAS and PD-L1 status) were found to display a significant correlation with IDO-1 positivity in tumor and immune cells." (PMID 40475772, 2025). "Anti-CTLA-4 antibodies can induce the upregulation of indoleamine 2,3-dioxygenase (IDO) expression in some HCC tumor cells, especially the IDO1 subtype." (PMID 41514551, 2025).
tumor (continued). "A central pathway involves activation of the aryl hydrocarbon receptor (AHR) by tumor-derived metabolites such as kynurenine, produced via indoleamine 2,3-dioxygenase 1 (IDO1), tryptophan 2,3-dioxygenase, or IL-4I1." (PMID 40800581, 2025). "IDO-1 expression occurs in tumor-draining lymph nodes, in the peri-tumoral stroma and in tumor tissue as well." (PMID 40475772, 2025). "Our analysis showed that IDO-1 expression was low in tumor cells but much higher in the stroma and immune infiltrate." (PMID 40475772, 2025). "Another inhibitor, Indoximod, relieves the inhibitory effects of IDO1-mediated tryptophan deprivation on mTOR signals needed in T cells for anti-tumour activity." (PMID 40430784, 2025). "Immunostaining confirmed substantially higher IDO1 expression in both mammary gland epithelial cells and tumor cells in PyMT-RIDad mice compared with PyMT controls (detailed images)." (PMID 40526430, 2025). "IDO1 expression in stromal cells contributes to the establishment of a tumor-promoting microenvironment and support tumor progression." (PMID 40287406, 2025). "Despite the potential of IDO1 as a target for tumor immunotherapy, clinical trials of IDO1 inhibitors are yet to show satisfactory outcomes." (PMID 41332472, 2025). "Collectively, these processes enable IDO1 to maintain immune tolerance within the tumor microenvironment, establishing it as a critical target for cancer immunotherapy and other immune-related diseases." (PMID 41209588, 2025). "-Serum Kyn and tumor IDO1 expression lower in ER+ vs. ER− patients.-Confirmed in larger datasets: lower IDO1 mRNA and protein expression in ER+ tumors.-Statistical significance: p < 0.01 and p < 0.001." (PMID 40650089, 2025). "IDO1 activity is known to promote immune tolerance within the tumor microenvironment, enabling evasion of T-cell-mediated surveillance and resistance to immune checkpoint blockade therapy." (PMID 40917745, 2025). "The inflammatory cytokine interleukin‐1β upregulates IDO1 expression, enhancing the conversion of Trp to Kyn, which exacerbates immunosuppression and tumor progression." (PMID 41332472, 2025). "This process is catalyzed by key enzymes, including indoleamine 2,3-dioxygenase 1 (IDO1) and tryptophan 2,3-dioxygenase 2 (TDO2) and the levels of these metabolites are closely associated with the malignant features of the tumour (Refs 6, 7)." (PMID 40040508, 2025). "Immunohistochemistry (IHC) analysis of the MC38 tumor tissues showed that MSA-2 exposure led to higher IDO1 expression in both early-stage and advanced tumors compared with that in the untreated tumors." (PMID 41129257, 2025). "It is widely recognized that IDO1, within the KP, suppresses tumor immunity by generating KYN, and inhibitors developed based on this mechanism, such as epacadostat and navoximod, have entered clinical trials." (PMID 40103267, 2025). "Elevated expression of tryptophan-2,3-dioxygenase 2 (TDO2) and indoleamine 2,3-dioxygenase 1 (IDO1) enhances kynurenine (Kyn) production, which fosters PCa progression through tumor-associated immunosuppression and direct pro-survival signaling." (PMID 41179661, 2025). "In sample HCC4, the tumor areas commonly expressed high IDO1, low PD‐L1 and CD274, and very low CTLA4." (PMID 41057994, 2025). "The role of IDO1 as a pivotal interface between inflammatory cytokines reflects its ability for creating an inflammatory environment that promotes tumor growth." (PMID 39371092, 2024). "While normally silenced in many tissues, IDO1 is highly expressed in the tumor cells of a wide range of human cancer types." (PMID 39211039, 2024). "Several preclinical mouse tumor models and the worse survival of patients bearing IDO1-expressing tumors support the relevance of IDO1-mediated immune suppression in the TME." (PMID 38333210, 2024). "This gap in understanding is significant, considering that both immune and tumor cells can express IDO1." (PMID 38706741, 2024).